PKHD1 (PKHD1 ciliary IPT domain containing fibrocystin/polyductin)
Diseases named in the same sentence as PKHD1 in open-access papers (continued):
Sharing a sentence is not in itself a finding about the gene and the disease.
cyst (continued). "In addition, to address whether treatment with Pkd1-null cell EVs/exosomes could promote cyst formation in normal mice, we treated Pkd1flox/+:Pkhd1-Cre mice with Pkd1-null cell EVs/exosomes or PBS from postnatal day 7 (P7) to 3-month old." (PMID 34315885, 2021). "Thus, in this model where the mechanism of renal failure is the destruction of normal renal architecture by cyst expansion, the provision of normal cells with wild type Pkhd1 may be more critical than the role of tubulogenic SAA1." (PMID 26136112, 2015). "Treatment with C-176 also decreased cyst growth as seen by a decrease of the cystic index, KW/BW, and BUN levels in Pkd1fl/fl: Pkhd1-Cre mice compared to that in age-matched vehicle-treated control mice." (PMID 39456148, 2024). "Inhibition of BRD4 with its inhibitor JQ1 delayed cyst growth and preserved kidney function in two PKD mouse models (Pkd1flox/flox:Pkhd1-Cre and Pkd1nl/nl)." (PMID 36120538, 2022). "We found that renal exosomes originating from normal Sprague Dawley cells carried and transferred wild type Pkhd1 mRNA to PCK cells in vivo and in vitro and restricted cyst formation by cultured PCK cells." (PMID 26136112, 2015). "Organoids were exposed to fluid‐flow on 3D millifluidic chips, resulting in the formation of cyst‐like structures in distal nephrons only in PKHD1−/− organoids and not in PKHD1+/− organoids." (PMID 39823139, 2025). "Our study reveals mitochondrial abnormalities in Pkhd1 KO kidney tubules despite the absence of cyst formation." (PMID 37845212, 2023). "Inhibition of glutaminase-1, which transforms glutamine into glutamate then catabolized into α-ketoglutarate, slowed cyst growth in Aqp2-Cre;Pkd1flx/flx but not in Pkhd1-Cre;Pkd1flx/flx mice." (PMID 36120538, 2022). "We found that administration of GW4869 (5 g/g) (n = 5) delayed cyst growth as seen by the decrease of cyst index, KW/BW ratio, and BUN level, and cystic epithelial cell proliferation in kidneys from Pkd1flox/flox: Pkhd1-Cre mice compared to controls." (PMID 34315885, 2021). "The effects of Pkhd1 on SMURF and RhoA activity may also contribute to cyst formation by other mechanisms." (PMID 28798345, 2017).
Renal cyst (17 papers, 2016 to 2025). A fluid filled sac in the kidney. "We identified biallelic PKHD1 variants in an individual presenting with kidney dysfunction and cystic kidney and liver morphology in adolescence." (PMID 41255767, 2025). "In contrast, we show that MYC abundance is unaltered in non-cystic kidneys from Pkhd1-deficient mice." (PMID 38125876, 2023). "miR-21 is also upregulated in cystic kidneys from Pkd1 conditional knockout mice (Pkd1flox/flox:Pkhd1-Cre mice), Pkd2 conditional knockout mice (Pkd2flox/flox:Pkhd1-Cre mice), and HNF1B conditional knockout mice (Hnf-1βflox/flox:Pkhd1-Cre mice), and in human ADPKD kidneys." (PMID 33809516, 2021). "Importantly, we observed extensive RGLS4326 uptake in both proximal tubules and collecting duct cysts in cystic kidneys of the aggressive Pkhd1/cre;Pkd2F/F (Pkd2-KO) mouse model of ADPKD following SC administration, likely linked to the severely disrupted kidney architecture in this mouse model." (PMID 31515477, 2019). "We found that the mRNA levels of transforming growth factor β (TGF-β), α-SMA, Col I and Col III were increased in cystic kidneys from PN21 and PN28 Pkd1flox/flox:Pkhd1-Cre mice versus those in kidneys from age matched wild type mice as examined by qRT-PCR analysis." (PMID 38534333, 2024). "In contrast, renal MYC expression levels were not altered in several Pkhd1 mutant mice that lack a significant cystic kidney phenotype." (PMID 38125876, 2023). "In contrast, MYC protein levels were not elevated in kidneys from four different Pkhd1 mutant mouse model lines (Pkhd1cyli, Pkhd1del3-4, Pkhd1del3-67, or Pkhd1del67) that did not exhibit a cystic kidney phenotype." (PMID 38125876, 2023). "Furthermore, the lack of enhanced MYC expression in Pkhd1 mutant mice without cystic kidney phenotype suggests differences in the function of mouse and human FPC-CTDs." (PMID 38125876, 2023).
liver disease (14 papers, 2009 to 2023). "For example, a genome-wide investigation of liver fibrosis in the Swiss Franches-Montagnes breed led to the identification of an associated region containing a promising candidate gene, PKHD1, which was also associated with kidney and liver disease in humans." (PMID 31861495, 2019). "We have previously revealed that there is no clear correlation between genetic confirmation status and clinical course of kidney and liver diseases in patients with at least 1 PKHD1 variant classified as VUS, LP, or P, including patients with only a single detected variant." (PMID 35812281, 2022). "Whereas phenotypes of the index patients with mutated PKHD1, TMEM67, and PPOX corresponded with those elsewhere reported, how F11R variation underlies liver disease remains unclear." (PMID 37471416, 2023). "Pathogenic PKHD1 variants are causative for polycystic kidney disease type 4 with or without hepatic disease, also known as autosomal recessive polycystic kidney and hepatic disease (ARPKD)." (PMID 34573383, 2021). "We said that we did not believe her existing liver disease had anything to do with this PKHD1 variant (and indeed, the hepatic ultrasound ordered for other reasons prior to the DTC report had found fatty infiltration but no cysts)." (PMID 24954083, 2014). "Although biallelic PKHD1 mutations were identified in only 43 families and one heterozygous mutation in 20 families, the authors concluded that kidney and liver disease are independent, and that variability in severity does not reflect the type of PKHD1 mutation." (PMID 24710345, 2014). "Similarly, kidney and liver diseases were independent of each other and variability in severity couldn't be not explained by the type of PKHD1 mutation in an ARPKD cohort." (PMID 32382272, 2020). "Although a range of PKHD1 mutations are associated with CS, the diagnosis is usually made through the characteristic clinical picture, typical imaging features with or without histological confirmation, and exclusion of other hepatic diseases leading to hepatic fibrosis and bile duct dilatation." (PMID 32993513, 2020). "This sexual dimorphism in cyli-related liver disease severity has not previously been reported for human PKHD1-related disease or in other genetically engineered Pkhd1 mouse mutants, possibly due to the paucity of longitudinal studies in both human patients and previously reported mouse models." (PMID 37584738, 2023).
Hepatic fibrosis (12 papers, 2014 to 2025). The presence of excessive fibrous connective tissue in the liver. "Studies have shown that PKHD1 mutations are responsible for congenital hepatic fibrosis and autoimmune cholangitis." (PMID 32898339, 2020). "Due to the recessive inheritance and the fatal effect of the mutation, we initially hypothesized that most likely a loss of function mutation affecting the coding sequence of PKHD1 would be responsible for the congenital hepatic fibrosis phenotype." (PMID 25295861, 2014). "Of note, 2 of the monoallelic PKHD1 cases also exhibited hepatic fibrosis, which would be consistent with ARPKD; however, interrogation of their genomes did not reveal a plausible second variant." (PMID 39190485, 2024). "For liver, a potential tissue-specific regulatory element was identified in the 59th intron of PKHD1 (Ensembl Transcript ID: ENSECAT00000024985.1), a gene which has been previously associated with liver fibrosis." (PMID 31861495, 2019). "A careful inspection of these genes and database searches of their presumed function revealed the polycystic kidney and hepatic disease 1 gene (PKHD1) as an excellent functional candidate gene for congenital hepatic fibrosis in horses." (PMID 25295861, 2014). "Several phenotypes are associated with mutations in PKHD1: congenital hepatic fibrosis, biliary tract abnormality and absence of renal corticomedullary differentiation." (PMID 30791866, 2019). "We speculate that these mechanisms may explain the increased TGF-β signaling previously reported in Pkhd1 livers and contribute to the hepatic fibrosis that is a universal feature of ARPKD." (PMID 28798345, 2017). "Whereas most pathogenic PKHD1 variants lead to polycystic defects in kidney and liver, a small subset of the human ARPKD patients have only liver symptoms, similar to our horses with congenital hepatic fibrosis." (PMID 25295861, 2014). "We identified two missense variants in the PKHD1 gene which were strongly, but not perfectly associated with congenital hepatic fibrosis." (PMID 25295861, 2014). "Interestingly, not all patients with PKHD1 and TMEM67 variants showed elastographic signs of liver fibrosis." (PMID 40247009, 2025). "No mutation of the PKHD1 gene was discovered in this girl, and the diagnosis of ARPKD was later ruled out when hepatic micronodular cirrhosis with steatosis was confirmed at liver biopsy, and congenital hepatic fibrosis was excluded." (PMID 26695994, 2015). "Therefore, congenital hepatic fibrosis might not be as frequent as in PKHD1-related disease." (PMID 35211789, 2022).
autosomal dominant polycystic kidney disease (9 papers, 2017 to 2023). Autosomal dominant form of polycystic kidney disease. "A similar inheritance pattern explained some rare severe and early onset cases of autosomal dominant polycystic kidney disease when hypomorphic PKD1 mutations were co-inherited with variants in the PKHD1 or the HNF-1β gene." (PMID 28334007, 2017). "In particular, fibrocystin (PKHD1) is involved in autosomal recessive polycystic kidney disease (ARPKD), while polycystin-1 (PKD1) and polycystin-2 (PKD2) are implicated in autosomal dominant polycystic kidney disease (ADPKD)." (PMID 33339422, 2020).
ciliopathies (8 papers, 2019 to 2026). "We found a lower lifetime risk of 1 in 34,602 to 1 in 44,052 for PKHD1 alone; however, when combining all ciliopathy genes, lifetime risk was higher between 1 in 7138 to 1 in 8292." (PMID 40677321, 2025). "This supports a link between medullary sponge kidney and ciliopathies, as suggested by the association with PKHD1 variants." (PMID 40973923, 2025). "WES revealed biallelic variation in 3 ciliopathy genes (PKHD1, TMEM67 and IFT172) in 4 clinically unrelated index subjects (3 children and 1 adult), heterozygosity for a known variant in PPOX in one adult index subject, and homozygosity for an unreported splice-site variation in F11R in one child." (PMID 37471416, 2023).
liver cysts (8 papers, 2020 to 2025). "Mice with homozygous Pkhd1 mutations have kidney and liver cysts that were aggravated by reduced Pkd1 dosage." (PMID 41300696, 2025). "The majority of parents of children with ARPKD do not present any symptoms of the disease, although monoallelic loss of PKHD1 has been observed in 10% of parents of ARPKD carriers who had asymptomatic liver cysts." (PMID 41300696, 2025). "The presence of multiple large cysts in the liver is not typical for ARPKD, although a subset of individuals who carry the PKHD1 mutation develop small focal liver cysts." (PMID 41300696, 2025). "Mild phenotypes with kidney and liver cysts may be seen commonly in carriers of PKHD1 disease-causing variants and should be considered in patients with medullary calcinosis and/or liver cysts." (PMID 37962562, 2024). "Additionally, data in mice suggest that heterozygous PKHD1 carriers may develop ARPKD-associated liver cysts only later in life after the occurrence of a second hit affecting the PKHD1 wild-type allele in somatic tissues." (PMID 34249099, 2021). "The causative genes of severe liver cysts were five variants in PKD1, one variant in GANAB, and one variant in PKHD1." (PMID 36833371, 2023). "The impact of modifying genetic or environmental factors on gene expression cannot be excluded, since not all PKHD1 carriers develop liver cysts." (PMID 41300696, 2025). "The patient also had a PKHD1 VUS; however, the clinical presentation (large cystic kidneys, absence of liver cysts, and early kidney disease progression) is more consistent with the PKD1 variant as the more likely explanation for the disease." (PMID 37962562, 2024).
colorectal cancer (7 papers, 2020 to 2025). A primary or metastatic malignant neoplasm that affects the colon or rectum. "Mutations in PKHD1 have been found to be involved in the development and progression of colorectal cancer (CRC)." (PMID 38178618, 2024). "In this study of 3702 samples, mutations in the PKHD1 gene, frequently observed in colorectal cancer (CRC), were correlated with increased tumor mutational burden and microsatellite instability, but decreased chromosomal instability." (PMID 38178618, 2024). "Mutated FAT1 and PKHD1 and altered Hippo pathway genes were found to be enriched in early-onset colorectal cancer." (PMID 36439454, 2022). "The germline mutations of PKHD1 played a protective role in colorectal cancer." (PMID 32117908, 2020). "High PKHD1 mutations, on the other hand, may increase susceptibility to colorectal cancer." (PMID 36618928, 2022). "PKHD1 TRA identified in two African patients received a ‘cautionary’ PP-SV classification, as identified as potential oncogenic in colon cancer, while potential tumour suppressor in colorectal cancer." (PMID 40064858, 2025). "PKHD1 TRA identified in two African patients received a ‘cautionary’ PP-SV classification, as identified potential oncogenic in colon cancer, while potential tumour suppressor in colorectal cancer." (PMID 38947031, 2024).
polycystic liver disease (7 papers, 2020 to 2024). "This variant has been implicated as a heterozygous cause of polycystic liver disease and its enrichment in our cohort as a heterozygous entity provides evidence for the role of PKHD1 as a monoallelic cause of CyKD." (PMID 39190485, 2024).
Caroli disease (6 papers, 2014 to 2025). Caroli disease (CD) is a rare congenital liver disease characterized by non-obstructive cystic dilatations of the intra-hepatic and rarely extra-hepatic bile ducts. "Caroli disease (type V BD) has previously been associated with mutations in the polycystic kidney and hepatic disease 1 (PKHD1) gene." (PMID 40866840, 2025). "The aetiologies of most of the types of bile duct dilatation are unclear, except for Caroli’s disease, that is, Todani type V, which has been shown to be caused by the mutation of the PKHD1 gene on chromosome 6p12." (PMID 35508976, 2022). "This is especially adaptable for the detection of PKHD1 (including 66 exon) mutations in families with Caroli disease." (PMID 24710345, 2014). "In conclusion, we combined WES with Sanger sequencing to report a novel compound heterozygous genotype of PKHD1 causative of Caroli disease in a Chinese twin family." (PMID 24710345, 2014). "In the present study, therefore, we investigated a Chinese twin family with Caroli disease to detect PKHD1 mutations using WES, and to evaluate the clinical phenotype correlation associated with these mutations." (PMID 24710345, 2014). "Although severely affected ARPKD and CHF patients account for most known PKHD1 mutations, and patients with Caroli disease have a low rate of PKHD1 mutation detection, the genotype-phenotype associated with PKHD1 mutations is relatively complex." (PMID 24710345, 2014). "Mutations in polycystic kidney and hepatic disease gene 1 (PKHD1) are responsible for Caroli disease, and many causative mutations are known." (PMID 24710345, 2014). "In this work, we identified a causative compound heterozygous PKHD1 mutation in a Chinese twin family with Caroli disease." (PMID 24710345, 2014). "First, Caroli disease is frequently associated with genetic mutations such as PKHD1, which are involved in ciliary dysfunction and may contribute to abnormal immune regulation." (PMID 41039418, 2025). "Our findings indicate exome sequencing can be useful in the diagnosis of Caroli disease patients and associate a compound heterozygous genotype in PKHD1 with Caroli disease, which further increases our understanding of the mutation spectrum of PKHD1 in association with Caroli disease." (PMID 24710345, 2014). "To date, the function of PKHD1 is still unclear, and we know little about the relationship between the PKHD1 genotype and clinical phenotype in Caroli disease." (PMID 24710345, 2014). "We found a novel compound heterozygous genotype of PKHD1 (p.Val836Ala/p.Arg781*) in twin of a Chinese family with Caroli disease." (PMID 24710345, 2014). "In 2002, Ward and colleagues first screened PKHD1 mutations in 14 probands with ARPKD (some cases of ARPKD with mainly liver manifestations, including Caroli disease diagnosed in adulthood), and revealed that eight of the affected individuals were compound heterozygotes." (PMID 24710345, 2014). "Our study enlarged the genotype-phenotype correlations of PKHD1, which might be useful for understanding the pathophysiological mechanisms of Caroli disease." (PMID 24710345, 2014). "Other studies have suggested that mutations in the WDR19 gene can also lead to either Caroli disease or Caroli syndrome.Due to limited resources, none of the cases in this cohort underwent PKHD1 or ARPKD genetic testing." (PMID 41039418, 2025).
Kidney Cyst (6 papers, 2021 to 2025). Abnormal fluid filled sac within the kidney, either acquired or congenital. "We identified 11 patients who carried homozygous or compound heterozygous PKHD1 gene variants out of the 38 individuals with kidney cysts." (PMID 36835961, 2023). "In family DY2184, a total of three kidney cysts (one in the right kidney and 2 in the left kidney at age 25) were identified in II-1 where a likely pathogenic PKHD1 variant (p.Arg375Gln) was detected." (PMID 35778421, 2022). "While DNAJB11 is a known disease-causing gene of ADPKD, and kidney cysts can develop in patients who are heterozygous for a pathogenic variant in PKHD1, more evidence is required to determine whether heterozygous NEK8 and WDR19 pathogenic variants can mimic the ADPKD phenotype." (PMID 36833371, 2023). "In patients with the diagnosis of PKHD1, ALG8, and GANAB variants, kidney cysts tend to be less destructive than PKD1 and PKD2 with relatively preserved kidney contours." (PMID 35778421, 2022). "Whereas Pkhd1::Cre; Pkd2lox/lox mice had developed massive cysts at 4 weeks of age, we could not detect any kidney cysts in Pkhd1::Cre; Pkd2lox/poreL1 mice at the same age (data not shown)." (PMID 34345895, 2021).